TREM2 (triggering receptor expressed on myeloid cells 2)
Diseases named in the same sentence as TREM2 in open-access papers (continued):
Sharing a sentence is not in itself a finding about the gene and the disease.
Alzheimer disease (continued). "Furthermore, the increased risk of Alzheimer’s disease caused by TREM2 mutations has led to research showing many effects of TREM2 on phagocytosis, transcription, metabolism, and inflammation." (PMID 32450896, 2020). "Since the discovery of TREM2 (triggering receptor expressed on myeloid cells 2) variants as genetic risk factors for Alzheimer's disease (AD), TREM2 biology has become a focal point in research efforts to better understand how the innate immune system impacts AD and other neurodegenerative diseases." (PMID 31980586, 2020). "TREM2 is an Alzheimer's disease (AD) risk gene expressed in microglia." (PMID 31980586, 2020). "A proactive role of brain immune cells, microglia, in the pathogenesis of Alzheimer’s disease (AD) gained recognition after the discovery of AD-associated variants in the triggering receptor expressed on myeloid cell 2 (TREM2) gene that is only expressed on immune cells of myeloid origin." (PMID 33101276, 2020). "Our findings are thus compatible with increased expression of TREM2 in Alzheimer’s disease having a protective function slowing disease progression, and hence loss of function due to the presence of the Trem2 R47H mutation increasing the chance of AD reaching the stage of diagnosis." (PMID 32959884, 2020). "Rare variants in the TREM2 gene increase the risk for late-onset Alzheimer’s disease (AD)." (PMID 30630532, 2019). "The importance of neuroinflammation and microglia in Alzheimer’s disease has been highlighted by multiple GWAS, which have identified a number of single polymorphisms associated with risk for development of Alzheimer’s disease in several immune related genes, including TREM2, CD33, BIN1, and CR1." (PMID 31504240, 2019). "Moreover, the R47H TREM2 mutation increases the risk for Alzheimer's disease (AD) 3–4 fold and mutations in the TREM2 gene are thought to be linked with the impaired uptake of Aβ-lipoprotein complexes by microglia." (PMID 31379859, 2019). "This relationship with NHD prompted an effort to identify allelic variants in the TREM2 coding region that could also confer risk to Alzheimer’s disease." (PMID 31068200, 2019). "It will be interesting to determine if any macrophage-expressed TspanC8, namely Tspan5, Tspan14, Tspan17, or Tspan33, can promote TREM2 cleavage, and could thus be considered a therapeutic target for TREM2-associated Alzheimer’s disease." (PMID 30013551, 2018). "In addition to Alzheimer's disease, R47H and other variants of TREM2 are reported to be risk factors for PD, although this remains controversial." (PMID 30127720, 2018). "As TREM2 is a strong risk factor for Alzheimer's disease (AD) in humans and was recently demonstrated to be a critical regulator of microglial activity in mouse models of AD, many articles have reviewed the recent progress of TREM2/DAP12 research in AD." (PMID 30127720, 2018). "Loss of function of TREM2 may also contribute to the pathogenesis of Alzheimer’s disease, in which chronic inflammatory responses occur." (PMID 28592261, 2017). "Understanding the balance of delivery and loss of TREM2 at the cell surface might allow us to develop novel therapies to regulate neuroinflammation in Alzheimer's disease." (PMID 28855301, 2017). "Moreover, TREM2 mutations are associated with an increased risk of developing Alzheimer's disease, frontotemporal dementia and amyotrophic lateral sclerosis." (PMID 28303091, 2017). "It is less clear whether variants linked to Alzheimer's disease affect the levels of TREM2 at the cell surface." (PMID 28855301, 2017). "Loss‐of‐function mutations of TREM2 are associated with increased risk of Alzheimer's disease (AD)." (PMID 26941262, 2016). "For example, whole genome and whole exome sequencing has identified point mutations in the gene encoding the protein TREM2 (triggering receptor expressed on myeloid cells 2) that correlate with a significantly increased risk of developing Alzheimer’s disease (AD)." (PMID 27995897, 2016).
Alzheimer disease (continued). "Interestingly, TREM2 variants have recently been associated with late-onset Alzheimer’s disease (AD) and frontotemporal lobe dementia (FTD)." (PMID 26792193, 2016). "The identification of TREM2 variant is essential and will play a significant role as it poses a high risk for Alzheimer’s disease and due to the fact that the gene’s normal biological function resulted in reduced immune function which probably adding to disease onset." (PMID 24663666, 2014). "The gene was a previously implicated in a study by Inserm-Lille2-IPL UMR744, British, American, and French researchers have now shown that, on this same region of chromosome 6, mutations in the TREM2 gene are associated with a five-fold increased risk of developing late-onset Alzheimer’s disease." (PMID 24663666, 2014). "The mechanism by which TREM2 influences the susceptibility to Alzheimer’s disease is currently unknown." (PMID 24893973, 2014). "The identification of variants in TREM2 as an important cause of late-onset Alzheimer's disease raises the possibility that genes that are highly co-expressed with TREM2 might also be candidate genes for AD." (PMID 23855984, 2013). "Rare variants in TREM2 cause susceptibility to late-onset Alzheimer's disease." (PMID 23855984, 2013). "The interest in TREM2 as a genetic risk factor for neurodegenerative diseases greatly increased when two recent studies independently identified a rare missense mutation (rs75932628, p.R47H) in the TREM2 gene as an important risk factor for late-onset Alzheimer’s disease (AD)." (PMID 23800361, 2013). "Previously, TREM2 was extensively studied and identified as a surface receptor required for microglia response to neurodegenerative changes, which has been associated with the pathogenesis of Alzheimer’s disease (AD) and other neurodegenerative diseases (NDDs)." (PMID 38725629, 2024). "In the present study, I aimed to investigate the association between TREM2-related microglial responses and tau accumulation in the presence and absence of amyloid-beta pathology in order to give a better view of the role of microglial activation in Alzheimer’s disease development." (PMID 37942087, 2023). "In the present study, I aimed to investigate the association between TREM2-related microglial responses and tau accumulation in the presence and absence of Aβ pathology in order to give a better view of the role of TREM2-related microglial activation in Alzheimer's disease development." (PMID 37942087, 2023). "Further research found that mice with associated genes knockout in Alzheimer's disease showed decreased mTOR pathway activity, impaired glycolysis function and increased neuronal autophagy, especially the triggering receptor expressed on myeloid cells‐2 (TREM‐2) gene." (PMID 37132040, 2023). "Heterozygous loss-of-function mutations in TREM2, including mutations enhancing shedding form the cell surface, have been associated with myelin/neuronal loss and neuroinflammation in neurodegenerative diseases, such as Alzheimer`s disease and Frontotemporal Dementia." (PMID 36755323, 2023). "It is possible that the expected loss of function in TREM2 conferred by p.R47H may underlie the lower levels of TSPO signal seen in the TREM2 p.R47H carriers and that this reduced microglial activation may be a factor in the increased risk of Alzheimer’s disease in these carriers." (PMID 37990275, 2023). "In contrast, deletion of TREM2 or the adaptor tyrosine kinase-binding protein (TyroBP or DAP12), which binds to TREM2, leads to an excess of the pro-inflammatory phenotype, which decreases microglial survival and causes amyloid plaque deposition in experimental models of Alzheimer's disease (AD)." (PMID 35844208, 2022).
Alzheimer disease (continued). "Moreover, in an Alzheimer’s disease model, deficiency of TREM2 in microglia was associated with reduced phosphorylation of AKT and poor activation of the downstream transcription factor mTORC1, leading to altered metabolic pathways, cell death, and augmented neuronal dystrophy." (PMID 34838047, 2021). "Additionally, variations in the exosomal proteome influenced by the R47Hhet TREM2 variant may underlie the increased risk of Alzheimer’s disease associated with this variant." (PMID 34831089, 2021). "Genetic studies including genome-wide studies have also associated inflammation-related genes to the etiology of Alzheimer’s disease (i.e. ABCA7, CLU, CR1, HLA-DRB1, HLA-DRB5, PICALM, and TREM2), further supporting the concept of neuroinflammation as a pathogenic factor in Alzheimer’s disease." (PMID 34335238, 2021). "Genetic studies have identified loss-of-function mutations of TREM2 as the cause for a rare form of early-onset dementia with autosomal recessive inheritance, known as Nasu-Hakola disease, and many additional variants as rare but strong risk factors for developing Alzheimer’s disease." (PMID 31856864, 2019). "Interestingly, this is also the case for the TREM2 gene (encoding for Triggering Receptor Expressed on Myeloid cells 2), which seems to be the most frequent genetic risk factor of another common neurodegenerative disorder, Alzheimer’s disease (AD)." (PMID 31010158, 2019). "It was investigated whether TREM2 variants could also confer risk for Alzheimer’s disease." (PMID 28768545, 2017). "Therefore, an increase in TREM2+ microglia/monocytes may underlie the increased risk from a western diet to age-related neurodegenerative diseases such as Alzheimer’s disease." (PMID 26888450, 2016). "Triggering receptor expressed on myeloid cells 2 (TREM2), a microglial receptor critical for clearing neurotoxic Aβ and maintaining metabolic homeostasis, is dysfunctional in Alzheimer’s disease." (PMID 41484634, 2026). "UB-SCG-51 administration has been shown to lower the expression of pro-inflammatory cytokines, namely Il-1β, CCL3, CCL12, and Trem2, which are mediators of glial activation and contribute to Alzheimer’s disease progression." (PMID 41007636, 2025). "TREM2, an immune receptor expressed by microglia in the brain, plays an essential role in neurodegenerative diseases such as Alzheimer’s disease (AD) and PD." (PMID 40246829, 2025). "The third most cited paper titled, “Human and mouse single-nucleus transcriptomics reveal TREM2-dependent and TREM2-independent cellular responses in Alzheimer’s disease,” was published in 2020 in Nature Medicine and received 597 citations." (PMID 41017976, 2025). "AL002 is an investigational, humanized, TREM2-selective agonistic monoclonal antibody in Phase 2 trials for the treatment of early Alzheimer’s disease." (PMID 40401046, 2025). "Anti‐TREM2 agonistic antibody or sTREM2 recombinant injection ameliorated the pathology in Alzheimer's disease, making them appealing new treatments." (PMID 41058009, 2025). "Preclinical studies, but TREM2 agonists are being tested in Phase III clinical trials for Alzheimer's disease." (PMID 41139809, 2025). "Recently, an agonistic antibody targeting TREM2 (AL002; INVOKE-2 trial) was evaluated in patients with Alzheimer’s disease to test the therapeutic potential of modulating microglial function through the TREM2 pathway." (PMID 41373648, 2025). "This study demonstrates that the Alzheimer’s disease risk factor iRhom2/RHBDF2 is a modifier of microglial TREM2 proteolysis and establishes ADAM17 as a physiological TREM2 protease in microglia." (PMID 40081988, 2025). "Variants in genes associated with immune responses, such as TREM2 (triggering receptor expressed on myeloid cells 2) and CD33, have been linked to an increased risk of neurodegenerative diseases like Alzheimer’s disease (AD) and related disorders." (PMID 40004109, 2025).
Alzheimer disease (continued). "Established markers of Alzheimer’s disease and neurodegeneration, including TREM2, SAA1, CHIT1, CRP and PDGFRB demonstrated strong correlations (r > 0.8) in the comparison with SomaLogic measurements." (PMID 41250190, 2025). "The triggering receptor expressed on myeloid cells 2 (TREM2) has become a promising target for biologics in both monitoring and treating neuroinflammation in Alzheimer’s disease (AD)." (PMID 40434494, 2025). "Triggering receptor expressed on myeloid cells-2 (TREM2) variants have been identified as risk factors for neurodegenerative disease, including Alzheimer’s disease." (PMID 40400621, 2025). "Triggering Receptor Expressed on Myeloid Cells 2 (TREM2), a lipid-binding receptor expressed on the cell surface, has previously been shown to maintain the metabolic fitness of microglia in Alzheimer’s disease (AD)." (PMID 40636122, 2025). "Other known Alzheimer's disease–associated genes, BIN1, TREM2, ZCWPW1, and APH1B, were also replicated in our time-to-event GWAS." (PMID 40949174, 2025). "We chose Nefl and TREM2, which are under evaluation as potential key markers for neurodegeneration and microglial activation in Alzheimer’s disease." (PMID 40157722, 2025). "Our study elucidates a novel PU.1-mediated transcriptional regulation mechanism governing TREM2 expression, demonstrating its pivotal role in modulating microglial activation dynamics during the progression of Alzheimer’s disease." (PMID 40376093, 2025). "An analogous phenomenon has been observed for amyloid ß animal models of Alzheimer's disease, leading to early‐stage trials of TREM2 agonism to treat Alzheimer's disease." (PMID 40506843, 2025). "TREM2 is currently being explored as a pharmaceutical target in Alzheimer’s disease, via a novel high-affinity TREM2 antibody and small molecule agonist called VG-3927." (PMID 40700076, 2025). "Microglial dysfunction is characteristic of Alzheimer’s disease (AD), with triggering receptor expressed on myeloid cells 2 (TREM2) and transcription factor PU.1 playing crucial roles." (PMID 40376093, 2025). "TREM2 agonists have been shown to enhance microglial cell survival and function, offering a potential avenue for developing TREM2-targeting therapies for Alzheimer’s disease." (PMID 40940747, 2025). "Background/Objectives: TREM2 is a transmembrane receptor highly expressed in microglia and macrophages, and its involvement in Alzheimer’s disease, obesity, and cancer has garnered significant attention." (PMID 41300781, 2025). "Bridging integrator 1 (BIN1), triggering receptor expressed on myeloid cells 2 (TREM2), and zinc finger CW-type (ZCWPW1)/PWWP domain containing 1 (NYAP1) were identified in both all-cause dementia and Alzheimer's disease." (PMID 40949174, 2025). "Prior studies have mainly concentrated on the function and regulation of TREM2 in the development of neurodegenerative disorders, particularly Alzheimer’s disease." (PMID 40083551, 2025). "Previous studies have predominantly focused on the TREM2 signaling pathway in Alzheimer’s disease, metabolic syndrome, and cancer." (PMID 40083551, 2025). "In Alzheimer’s disease (AD), TREM2 participates in the clearance of amyloid plaques via phagocytosis." (PMID 40242752, 2025). "VG-3927 is a selective, brain-penetrant, oral small molecule TREM2 agonist currently under development for Alzheimer’s disease (AD)." (PMID 40806186, 2025). "In Alzheimer's disease, a reduction in TREM2 results in diminished microglial activity, triggering neuroinflammation and ultimately accelerating the aging process and neural loss." (PMID 38649789, 2024). "Trem2 has been extensively researched primarily on the capacity of microglia, which foster microglial responses to neurodegenerative diseases like Alzheimer’s disease." (PMID 39250507, 2024). "Soluble Triggering Receptor Expressed on Myeloid Cells 2 (sTREM2) plays a crucial role in the pathogenesis of Alzheimer’s disease (AD)." (PMID 38912524, 2024).
Alzheimer disease (continued). "Recent research underscores TREM2’s pivotal role in various diseases, including Alzheimer’s disease, obesity, fatty liver, arterial congee, stroke, and other diseases." (PMID 39323470, 2024). "Further, TREM2 binds oligomers of β amyloid, leading to the colocalization of DAMs and plaques in a rodent model of Alzheimer’s disease." (PMID 38247852, 2024). "TREM2, an immune signaling hub, plays a significant role in the progression and regression of diseases such as Alzheimer's disease, metabolic diseases, tumors, and sepsis." (PMID 39113887, 2024). "To prepare APOE and TREM2 ASO efficacy studies in disease-relevant mouse models of Alzheimer’s disease, we explored if ASOs can also target disease-relevant genes in human microglia in vivo." (PMID 38654375, 2024). "Clinical trials are currently investigating both monoclonal antibodies and small-molecule agonists designed to target TREM2, with the aim of translating these promising preclinical findings into effective treatments for Alzheimer’s disease." (PMID 39596011, 2024). "Given its involvement in various diseases, TREM2 holds promise as a potential therapeutic target for conditions particularly in Alzheimer's disease and cancer." (PMID 39113887, 2024). "Another study found the dual role of TREM2 in microglial cells in Alzheimer’s disease, where TERM2 was used to be considered to play only protective roles for Alzheimer’s disease." (PMID 39633897, 2024). "By regulating gene expression of inflammatory pathway inhibitors such as Trem2, S/G lipids merit broader investigation into the potential dysfunction of other innate immune cells, such as microglia, in diseases such as Alzheimer’s disease." (PMID 38989285, 2024). "Recent research has extensively investigated the specific expression of GRN and TREM2 on microglia, the brain-resident macrophages, revealing their links to neurodegenerative disorders such as frontotemporal lobar degeneration and Alzheimer’s disease." (PMID 39143467, 2024). "While an understanding of Nasu‐Hakola disease has led to a focus on Trem2 in Alzheimer's disease and dementia, there has been minimal focus on the role of Trem2 within bone." (PMID 38825965, 2024). "In the field of Alzheimer’s disease, soluble TREM2 (a transmembrane protein abundantly expressed on microglia) presents a promising biomarker associated with neuroinflammation." (PMID 39666067, 2024). "TREM2 is a signaling receptor expressed on microglia that has emerged as an important drug target for Alzheimer’s disease and other neurodegenerative diseases." (PMID 39315272, 2024). "For these and other reasons, TREM2 has emerged as a viable drug target for Alzheimer’s disease, especially in the preclinical stage." (PMID 39315272, 2024). "After the discovery of TREM2 mutations the study of a new target drug has been started (A Phase 2 Study to Evaluate Efficacy and Safety of AL002 in Participants With Early Alzheimer’s Disease - Full Text View - ClinicalTrials.gov, NCT04592874)." (PMID 37286172, 2023). "The soluble form of TREM2 (sTREM2) is reported to be increased in the cerebrospinal fluid of patients with Alzheimer’s disease, multiple sclerosis, and neurosyphilis as a marker of microglial activation during neuroinflammation." (PMID 37481571, 2023). "Most strategies to treat Alzheimer’s disease by targeting TREM2 found it most effective to stimulate TREM2 in the early stages of the disease." (PMID 37444065, 2023). "Gene therapies promoting overexpression of Trem2 are being investigated for treatment of Alzheimer’s Disease and other neuroinflammatory disease, while Trem2 neutralizing antibodies are being studied as a potential adjuvant to immunotherapy for solid tumors." (PMID 37901247, 2023). "In our manuscript, we explored the shared pathways between glioblastoma (GBM) and Alzheimer’s disease (AD), highlighting NF-κB, miRNA, and TREM2 as key examples, especially focusing on microglia and macrophages in the disease situation." (PMID 38203185, 2023).